CCR3 (C-C motif chemokine receptor 3)
Diseases named in the same sentence as CCR3 in open-access papers (continued):
Sharing a sentence is not in itself a finding about the gene and the disease.
asthma (continued). "In addition, a decrease in ccr3 gene expression in the lung by menthone inhalation might not have been an entire mechanism but partially resulted from reduced infiltration of eosinophils, neutrophils, etc., into the lungs, due to less allergic inflammation in asthma cases." (PMID 35409371, 2022). "Besides inhibition of eotaxin-1 and MCP expression by simvastatin, neither IL-13 nor simvastatin treatment changed the expression of other asthma-relevant Th2-type cytokines such as IL-4, CCL5 (RANTES), CCR3, or IL-5Ra." (PMID 22583375, 2012).
COVID-19 (24 papers, 2020 to 2025). A disease caused by infection with severe acute respiratory syndrome coronavirus 2. "Additionally, we found a significant association between severe COVID-19 and rs35775079, a variant located in the intronic region of CCR3 (p = 0.02; OR = 8.53)." (PMID 38605121, 2024). "Of these genes, 7 are chemokine receptor genes (CCR1, CCR2, CCR3, CCR5, CCR9, CCRL2, and CXCR6), which are likely linked to the segment’s association with COVID-19 severity." (PMID 36763080, 2023). "CCR3 expression was reduced in basophils from severe and critical COVID-19 cases (Bonferroni-adjusted P-value range 0.01–2.11 × 10−7)." (PMID 36433939, 2022). "Basophils expressed reduced levels of CCR3 early after symptom onset while levels were closer to unexposed healthy individuals at later timepoints within the severe COVID-19 group (Spearman’s rank correlation; R2 = 0.46, P = 2.8 × 10−4)." (PMID 36433939, 2022). "One can see a large block of SNPs in high LD, encompassing some of CCR3’s 5’UTR and most of its gene body, all having positive associations with both severe COVID-19 and M05B drug prescription." (PMID 36156592, 2022). "In this regard, a gene cluster on chromosome 3 containing CCR1, CCR3, CXCR6, and CCR9, has been identified as a major risk factor for COVID-19 at the genome-wide level (Zeberg and Pääbo, 2020)." (PMID 36320810, 2022). "CCL11 (eotaxin-1) which acts through receptor CCR3 was found to be increased in the earlier phase of COVID-19 and its levels remained steady post infection (Khalil, Elemam & Maghazachi, 2021)." (PMID 36353605, 2022). "In severe COVID-19 patients, the frequencies of CCR6+cTfh cells and CCR4+cTfh cells were expanded, but CCR3+cTfh cells and Th1 cells were low in severe COVID-19 patients compared to healthy individuals." (PMID 34603308, 2021). "Our analysis revealed a strong signal of coherence between COVID-19 and M05B medications, with chemokine receptor genes CCR1, CCR3 and LZTFL1 as lead hits." (PMID 36156592, 2022). "Dissecting the Th cell phenotypes, we observed an apparent lower CXCR3+Th1 subset, along with higher CCR3+Th2 and CCR5+Treg frequencies, in our COVID-19 cohort." (PMID 33808906, 2021). "Chemokine receptors, such as CCR9, CXCR6, CCR1, CCR3, CCR5, and CCR2, are all located on chromosome 3 and already showed significant associations with COVID-19 without network boosting." (PMID 36291657, 2022). "Meanwhile, the anti-inflammatory subset Th2 and Treg, represented by CCR3+CD3+CD4+ and CCR5+CD25+CD3+CD4+ markers, respectively, both the naïve and memory phenotypes, were upregulated in our COVID-19 cohort relative to HCs, suggesting immunoregulation and counter-inflammatory mechanisms." (PMID 33808906, 2021). "In addition, although receptors involved in chemotaxis, such as CRTH2 or CCR3, were not changed or were only slightly reduced, we, however, cannot totally rule out that blood eosinophils during COVID-19 represent a small and unique population that have not been recruited into the tissue." (PMID 40710346, 2025).
allergic disease (20 papers, 2004 to 2025). An immune response that occurs following re-exposure to an innocuous antigen, and that requires the presence of existing antibodies against that antigen. "CCR3 is a G protein-associated membrane receptor largely present on eosinophils and related to UC and allergic diseases." (PMID 40333150, 2025). "CCR3 is primarily expressed on the membrane of eosinophils, basophils, monocyte-derived dendritic cells, and a subset of Th2 lymphocytes involved in allergy and immune-mediated inflammation." (PMID 38203391, 2023). "In particular, we demonstrated that Ephedra Herb is a potential medical agent for TH2-mediated allergic diseases by inhibiting the cell migration mediated by the TH2-relevant chemokine receptors such as CCR3, CCR4, and CCR8." (PMID 27376063, 2016). "Collectively, CCR3 is of great value in modulating IL-5-induced chemotaxis, a key step in the allergic reaction, in both BA-E cells and human primary eosinophils." (PMID 27275740, 2016). "Antagonists of IL-5 and CCR3 have been found to have marked potential for inhibition of eosinophil recruitment in allergic diseases." (PMID 27275740, 2016). "Induction of upregulated expression of CD63 and CCR3 on passively sensitized human basophils (sera from American CR allergy patients) by approximately up to 4.5- and 3.2-fold indicates that iPer a 5 and bPer a 5 are functionally active." (PMID 24707117, 2014). "For example, subsets of TH2 cells have been shown to selectively express CCR3, which plays a role in basophil and eosinophil recruitment, reinforcing the suggestion that CCR3 is an important chemokine receptor in the expression of allergic disease." (PMID 20220260, 2010). "Eotaxin is a chemotaxin that binds with high affinity and specificity to the chemotaxin receptor CCR3 and plays an important role in the pathogenesis of allergic disease." (PMID 15537425, 2004). "CCR3 is expressed on eosinophils, making the chemoattraction of these cells the most significant feature of CCR3 ligands, and thus, their participation in allergic reactions and diseases." (PMID 39409868, 2024). "In particular, mouse models suggest a complex role of CCR3 in allergic diseases." (PMID 36156592, 2022). "Similarly to CCR3, CXCR3 has been implicated in the progression of numerous diseases, including but not limited to multiple sclerosis, rheumatoid arthritis, transplant rejection, systemic lupus erythematosus, and allergies." (PMID 37834457, 2023). "The inhibition of CCR3, one of the most specific chemokine receptors responsible for eosinophil trafficking, may contribute significantly to the suppression of inflammatory cell recruitment in eosinophil-dominant allergic diseases." (PMID 27275740, 2016). "Therefore, the eotaxin/CCR3 axis is the main control of mast-cell-mediated allergy." (PMID 24916929, 2014). "Collectively, these data strongly suggest that CCR3 and CCR4 are important therapeutic targets for a variety of allergic diseases." (PMID 27376063, 2016). "Chemokine receptors CCR3 and CCR4 are preferentially expressed by TH2 cells, mast cells, and/or eosinophils, all of which are involved in the pathogenesis of allergic diseases." (PMID 27376063, 2016). "As TH2 cells selectively express CCR3, CCR4, and CCR8, these data suggest that Ephedra Herb has a potency to strongly suppress cell migration of TH2 cells and TH2 cell-mediated allergic reactions." (PMID 27376063, 2016). "In this regard, CC chemokine receptor 3 (CCR3) is selectively expressed by eosinophils, basophils, and a part of TH2 cells that play major roles in allergic diseases." (PMID 27376063, 2016). "iPer a 5 and bPer a 5 at 1.0 μg/mL induced approximately up to 4.5- and 3.2-fold increase in the expression of CD63 and CCR3 in CD63 and CCR3 double positive cells when incubating with passively sensitized basophils (by sera from American CR allergy)." (PMID 24707117, 2014). "Therefore, CCR3 and CCR4 have long been highlighted as potent therapeutic targets for allergic diseases." (PMID 27376063, 2016).
allergic disease (continued). "As CCR3 is a receptor for eotaxins, RANTES, the monocyte chemotactic proteins, and plays a major role in allergic diseases, upregulated CCR3 expression is likely to participate in the development of AA and ARA, and could be a marker for the auxiliary diagnosis of AA and ARA." (PMID 40534099, 2025). "Thus, CCR3 and CCR4 have been paid attention as potent therapeutic targets for allergic diseases." (PMID 27376063, 2016).
eosinophilia (20 papers, 2013 to 2025). "Ccl11-deficient mice and neutralizing Ccr3 reduce pulmonary fibrosis, decreasing eosinophilia and neutrophilia, and profibrotic cytokine." (PMID 39768150, 2024). "While IL-4Rα KO mice were still able to generate eosinophilia and controlled the infection, mice became susceptible after depleting eosinophils through CCR3." (PMID 36389745, 2022). "The authors found that an EOTAXIN-2 gene variant: EOT-2+304C>A (29L>I), was significantly associated with blood eosinophilia (p = 0.0087) by the effect of CCR3 = -0.68." (PMID 32866209, 2020). "CCR3 deficiency rendered a profound, sustained impairment in tissue eosinophilia throughout the course of B. malayi infection." (PMID 29547639, 2018). "We further addressed CCR3-dependency of tissue eosinophilia and impact on immunity to B. malayi by using CCR3 deficient mice where steady state eosinophils in peripheral circulation are maintained but their CCR3-dependent tissue recruitment is ablated." (PMID 29547639, 2018). "Recently, we have defined a mechanism of adaptive immune control against invading B. malayi filarial larvae that is mediated by IL-4–IL-4R alternative activation of peritoneal macrophages and resultant CCR3-dependent tissue eosinophilia." (PMID 32571840, 2020). "In summary, our data confirm the pivotal role of eosinophils in the control of the filarial infection and reinforces the importance of CCR3-dependent eosinophilia in mediating immunity to the human filarial pathogen, B. malayi." (PMID 32571840, 2020). "We determine that IL-4-dependent alternative activation and expansion of Mφ are essential to regulate eosinophil-dependent immunity to filarial helminth infection via amplifying and sustaining CCR3-dependent tissue eosinophilia." (PMID 29547639, 2018). "Together these data indicate that ligation of IL-4Rα and subsequent BmL3AAMφ development augments tissue eosinophilia via CCR3 chemotaxis during the adaptive immune response to infection." (PMID 29547639, 2018). "In our B. malayi BALB/c infection model, CCR3-mediated chemotaxis was fundamental in the AAMφ-dependent eosinophilia during Brugia larval infection as blocking CCR3 signalling ablated eosinophil recruitment to the peritoneum." (PMID 29547639, 2018). "The parasitological outcome of IL-4/IL-4Rα activation of BmL3AAMφ and CCR3-dependent tissue eosinophilia was a significant reduction in B. malayi larvae in SCID mice +14dpi." (PMID 29547639, 2018). "Inhibition of GM-CSF/IL-3/IL-5 signaling by ASOs targeting the βc of their receptors or CCR3 expression in vivo suppressed antigen-induced eosinophilia and AHR in rat models of allergic asthma." (PMID 28106744, 2017). "A recent animal study has demonstrated that attenuation of ileal eosinophilia via CCR-3 inhibition leads to a reduction in fibronectin expression and substantial reduction in the histological markers of remodelling." (PMID 23717571, 2013). "In fibrosing alveolitis, macrophages (CD68+) and eosinophils are key sources of CCL5, with CCL5 correlating with eosinophil numbers in pulmonary fibrosis caused by sulfur mustard gas inhalation, suggesting a potential role of CCL5 in acting on CCR3 and contributing to eosinophilia during fibrosis." (PMID 39768150, 2024). "In clinical studies with asthmatics, it was shown that treatment with an anti-sense TPI ASM8 (4 mg bid and 8 mg o.d. inhaled for 4 days) directed against the β common chain and CCR3, attenuated Ag-induced airway eosinophilia as well as CCR3+HPC and EoP numbers." (PMID 33669458, 2021). "In a previous investigation, we reported that macrophages polarized to an alternatively activated phenotype through IL-4R activation mediated immunity to the human lymphatic filarial pathogen, Brugia malayi, by sustaining a vigorous CCR3-dependent eosinophilia at the site of infection." (PMID 32571840, 2020).
eosinophilia (continued). "The residual eosinophilia was maintained throughout the time course of infection in IL-4Rα−/− mice and was significantly elevated compared with corresponding CCR3−/−-infected animals at 5 wk (p = 0.05) or 12 wk postinfection (p = 0.05; Dunn multiple comparisons tests)." (PMID 32571840, 2020). "Therefore, our infection model indicated CCR3-dependent processes and recruitment of residual eosinophilia were sufficient to exert immune control of fecund infections in the absence of IL-4R signaling." (PMID 32571840, 2020). "We next examined whether BmL3AAMφ were necessary in CCR3-dependent tissue eosinophilia during infection." (PMID 29547639, 2018). "Using an oral CCR3 inhibitor, tissue eosinophilia could be blocked in the face of rIL-4 treatments and BmL3 infection." (PMID 29547639, 2018). "CCL5 regulates a variety of immune cells, including the transport of T cells, monocytes, eosinophilia, etc., which can bind to at least four receptors, including CCR1, CCR3, CCR5 and GPR75, among which CCR5 is the main receptor of CCL5 in adipose tissue." (PMID 40725440, 2025). "Taken together, reduced expression of CCR3 on eosinophils and CCL24/eotaxin-2 in the airways could potentially explain the decrease in airway eosinophilia observed in mice given rapamycin in addition to IL-33." (PMID 35720347, 2022). "Our data indicate that both CCR3-dependent ligands and IL-5 are necessary to induce eosinophilia to filarial infection in the absence of IL-4R signaling." (PMID 32571840, 2020). "The impaired eosinophilia evident at the infection site using either eosinophil-lineage depleted or CCR3-/- mice did not impinge on Mφ expansions post-infection." (PMID 29547639, 2018). "It has been shown that combining ASOs targeting βc and CCR3 simultaneously was superior in preventing antigen-induced eosinophilia and AHR, rather than employing ASOs against either target alone." (PMID 28106744, 2017). "Contrastingly, eosinophilia was not apparent in infected CCR3−/− mice (median level: 0.04 × 106)." (PMID 32571840, 2020). "Alternatively, IL-5 may be working as an independent chemotactic factor by which both IL-5R ligation and CCR-3 ligation are nonredundant signals combining to mediate peritoneal tissue eosinophilia in response to filarial parasitism." (PMID 32571840, 2020). "Eosinophil infiltration and peripheral eosinophilia are dependent on the eosinophil-specific cytokine (IL-5) and chemokines (eotaxin and RANTES), which provoke an eosinophilic response in the peripheral blood and airways via the C-C chemokine receptor type 3 (CCR3)." (PMID 29062168, 2017). "A consideration from these studies is that the local eoisnophilopoietic process may not be affected by CCR3 antagonism, thus targeting processes in both trafficking to the airways and differentiation within the airways may have a more profound effect on airway eosinophilia." (PMID 33669458, 2021).
breast cancer (19 papers, 2016 to 2025). A primary or metastatic malignant neoplasm involving the breast. "CCL7 is a ligand for CCR1–3 receptors, among which expression of CCR3 has recently been shown to be associated with luminal-type breast cancers." (PMID 31419632, 2019). "Our data indicate that intratumoral expression of CCR3 in breast cancer is associated with improved relapse-free survival in patients with luminal-like disease." (PMID 27086913, 2016). "When we confined the analysis in samples without peritumoral stromal CCR3 expression, intratumoral expression of CCR3 was associated with breast cancer subtype (P=0.04)." (PMID 27086913, 2016). "The aim of this study was to detect the expression of CCR3 in both breast tumor and tumor stroma, and to investigate the association of CCR3 expression with different breast cancer subtypes." (PMID 27086913, 2016). "These previous findings are in agreement with our present study, and the CCL5/CCR5 axis may be associated with the less aggressive phenotype of breast cancer in contrast to CCR3." (PMID 33671956, 2021). "The association chemokine receptor CCR3 with breast cancer subtypes and relapse-free survival is unknown." (PMID 27086913, 2016). "However, to our best knowledge, few studies have addressed the association between CCR3 and breast cancer, especially for different breast cancer subtypes." (PMID 27086913, 2016). "On the other hand, it has been reported that a higher expression of CCR3 mRNA was correlated with an improved relapse-free survival of breast cancer patients." (PMID 33671956, 2021). "For example, it has been reported that CCR3 is highly expressed in breast cancer samples, especially luminal-like subtype." (PMID 29121993, 2017). "We not only found the protective effect of CCR3 in unselected population, but also successfully repeated the outcomes in patients without adjuvant systemic treatment, indicating a robust and steady effect of CCR3 on breast cancer relapse." (PMID 27086913, 2016). "Previous research also suggested that CCL5/CCR3 signaling pathway is involved in prognosis and immunotherapy of luminal breast cancer." (PMID 27086913, 2016). "Furthermore, the survival curve of the patients with CCL5/CCR3 double-positive breast carcinomas was almost same as the others." (PMID 33671956, 2021). "CCL5 immunoreactivity was correlated with the aggressive phenotype of breast carcinomas only in the CCR3-positive group, and we speculated that the CCL5-CCR3 interaction might have important role in tumor progression." (PMID 33671956, 2021). "A similar scenario might take place in breast cancer since the CCL7 receptor CCR3 has been described to be widely expressed in breast tumor cells." (PMID 31963450, 2020). "Furthermore, higher expression of CCR3 is significantly associated with improved RFS in luminal-A and luminal-B cases, suggesting that CCR3 may reduce or delay metastases in breast cancer." (PMID 27086913, 2016). "Interestingly, when peritumoral stromal CCR3 was weak or absent, intratumoral expression of CCR3 was associated with breast cancer subtype (P=0.04)." (PMID 27086913, 2016). "On the other hand, the immunoreactivity of CCR1, CCR3 and CCR5 were observed in the cytoplasm of breast carcinoma cells." (PMID 33671956, 2021). "In contrast, CCR3 positive rate was relatively low in TNBC or HER2-enriched cancers, implied that the diverse effect of CCR3 in development of different breast cancer subtypes." (PMID 27086913, 2016). "The interaction between CXCL6 secreted by breast cancer cells and CXCR6 on naïve MSCs leads to the induction of CXCL10 secretion by MSCs, which in turn acts on CCR3 on breast cancer cells, facilitating the recruitment of MSCs and promoting breast cancer metastasis." (PMID 40676710, 2025).